EGFR (epidermal growth factor receptor)
Diseases named in the same sentence as EGFR in open-access papers (continued):
Sharing a sentence is not in itself a finding about the gene and the disease.
cancer (continued). "A multinational, interdisciplinary group of experts in supportive care in cancer reviewed relevant studies using established criteria to develop recommendations for dermatologic toxicities associated with EGFR inhibitors." (PMID 36990917, 2023). "The cellular function of CMTM8 has been associated with endocytosis of the EGFR, a receptor with tyrosine kinase activity, whose levels or activity are affected in many types of cancers." (PMID 37345137, 2023). "Since bypass RTK reactivation and/or tertiary EGFR mutations represent the majority of osimertinib-resistant cancers, these data suggest that targeting SOS2 has the potential to eliminate the majority of osimertinib resistance." (PMID 37425733, 2023). "The most common biomarkers are tumor-specific antigens such as HER2/neu for breast cancer, genetic mutations such as EGFR mutation of lung cancer, or cancer-associated proteins like PSA for prostate cancer." (PMID 37654932, 2023). "The EGFR (Epidermal Growth Factor Receptor) is crucial in cancer due to its frequent overexpression or mutations." (PMID 37764362, 2023). "Our study suggests that dynamic evaluation of genomic profile, especially oncogenic drivers such as EGFR mutational status, at cancer recurrence or relapse (or second primary) is warranted to tailor subsequent individualized therapy." (PMID 37503313, 2023). "In previous Korean studies, the NGS-based platforms (Oncomine Lung cfDNA and Pan-Cancer Cell-Free Assays) were more sensitive than the cobas® EGFR Mutation Test v2 for the detection of mutations with a VAF of 0.1." (PMID 37372399, 2023). "Subsequently, we selected a specific protein, epidermal growth factor receptor (EGFR), which is known to be associated with various types of cancer and is a popular target for cancer therapy." (PMID 37176031, 2023). "In humans, abnormal activation of EGFR is associated with the development and progression of many cancer types, which makes it an attractive target for molecular-guided therapy." (PMID 38201251, 2023). "The finding of strong associations between cancer drivers, such as EGFR, KRAS and MET and their associated enhancers, further stresses the importance of epigenetic and genetic interaction during tumorigenesis." (PMID 37914932, 2023). "EGFR (epithelial growth factor receptor) is an important player in normal cell proliferation, but mutations or upregulation in EGFR are associated with many cancers." (PMID 36672382, 2023). "Gefitinib, an epidermal growth factor receptor (EGFR) inhibitor, is effective in cancers that have activated mutations in EGFR." (PMID 36819091, 2023). "For example, gefitinib was found to effectively eliminate EGFR-mutated lung ADCs at the beginning of therapy, but the cancers recurred in 90% of patients within 2 years." (PMID 36899846, 2023). "Subsequently, the same investigation was conducted using cancer cells derived from one patient with an EGFR exon 19 deletion and T790M mutations." (PMID 36831438, 2023). "And mutations in the EGFR, especially the T790M/L858R double mutation, have made cancer treatment more difficult." (PMID 37528485, 2023). "While both c-Met and EGFR are known to form complexes with E-cadherin in cancer cells, the formation of such complexes is usually associated with inhibition of c-Met or EGFR phosphorylation." (PMID 37611070, 2023). "The occurrence and clinical relevance of the EGFR L858R mutation exhibit variability across distinct cancer types and diverse populations." (PMID 38273823, 2023). "Previously, several studies revealed that concurrent mutations would deteriorate the anti-cancer effect of EGFR-TKIs in patients with EGFR mutations." (PMID 37296463, 2023). "Aberrant EGFR signaling, often caused by overexpression, gene mutations, or amplification, is frequently observed in various cancer types, including GBM." (PMID 37947601, 2023).
cancer (continued). "In many carcinomas, EGFR overexpression and its mutation are involved in sustaining proliferative signaling, which is an important hallmark of cancer." (PMID 37489364, 2023). "Overexpression and hyperactivation/hyper-phosphorylation of EGFR has been linked to anoikis resistance in a range of cancers, including hepatocellular carcinoma, GBME, breast, lung and prostate cancer." (PMID 37181747, 2023). "The transition of the A-loop and αC-helix between active and inactive states is critical for EGFR regulation, and mutations associated with cancer dysregulate these conformations." (PMID 38035047, 2023). "The accurate identification of patients with KRAS or EGFR mutations is critical for the planning of individualized therapeutic strategies, as these mutations have been shown to play a significant role in cancer progression and response to treatment." (PMID 37508774, 2023). "This contrasts with other cancer types, where K-Ras mutation seems to negate the need for the stimulation of EGFR." (PMID 36975534, 2023). "One potential strategy to boost the immune response to these cancers would be to vaccinate patients with DNA encoding EGFR or ALK, or peptides taken from the sequences of the proteins they encode." (PMID 37795653, 2023). "This means that the resistance mutations that lead to cancer progression occur both in the EGFR gene itself and in other genes providing associated functions, which make aggressive tumors insensitive to further treatment." (PMID 37754201, 2023). "In cancer, inappropriate EGFR activation is triggered by amplification, point mutations, transcriptional upregulation, and ligand overproduction induced via autocrine/paracrine pathways." (PMID 37754880, 2023). "Abnormal activation of the EGFR was believed to be a major cause of malignant transformation and cancer metastasis." (PMID 37270563, 2023). "Both furmonertinib and its main metabolite (AST5902) can effectively treat cancers with EGFR sensitive mutations and T790M drug-resistant mutations." (PMID 38206746, 2023). "Nuclear EGFR was strongly correlated with poor OS in several cancer types, was associated with drug resistance, and was found to be involved in regulating genes needed for cell proliferation." (PMID 37444399, 2023). "In this retrospective study, we enrolled advanced NSCLC patients (IIIB-IV) with EGFR mutations who were first diagnosed and treated at Yunnan Cancer hospital from January 2016 to December 2019." (PMID 37881485, 2023). "Activation of the EGFR signaling pathway in cancer cells has been linked with increased cell proliferation, angiogenesis and metastasis." (PMID 37660139, 2023). "Further pathway leading to increased cancer cell survival are mutations associated to EGFR overexpression, found in adenocarcinoma of the lung, and colorectal cancer." (PMID 37427115, 2023). "Cancer in a small number of patients with EGFR mutations will transform from LUAD to small cell lung cancer (SCLC) during epidermal growth factor receptor tyrosine kinase inhibitor (EGFR-TKI) therapiesr." (PMID 37583423, 2023). "The epidermal growth factor receptor (EGFR) plays a crucial role in regulating cellular growth and survival, and its dysregulation is implicated in various cancers, making it a prime target for cancer therapy." (PMID 38273823, 2023). "Targeted EGFR therapy plays an important role in cancer therapy for patients bearing this mutation and can prolong the patient survival time." (PMID 37345192, 2023). "We showed that the expression of PAI-1 and mesenchymal genes in EGFR-mutated cancer cell lines was upregulated after developing tolerance to EGFR-TKIs in vitro." (PMID 36831438, 2023). "Recent findings suggest that cancers with EGFR mutations are associated with an increased incidence of diffuse lung metastases." (PMID 37122754, 2023).
cancer (continued). "The development of ATP-competitive small-molecule EGFR inhibitors demonstrated the significance of these EGFR mutations for cancer growth." (PMID 36902723, 2023). "We found that most top cancer-related mutations: EGFR and PIK3CA, were shared across matched adenomatous and squamous pathologies in all four samples." (PMID 37051524, 2023). "Apart from that, the PI3K/AKT/mTOR signaling pathway can activate EGFR and mutate among various malignant tumors, including leukemia and NSCLC." (PMID 37744063, 2023). "In tumors bearing EGFR amplification and/or activating mutations, cancer cells become addicted to the oncogenic function of EGFR, making EGFR an attractive therapeutic target." (PMID 37766136, 2023). "Wong’s group showed that treatment of cancer cells with a sialidase enzyme caused an increase in EGFR activation, which was attributed to enhanced EGFR clustering." (PMID 37660914, 2023). "In these cases, cancer proliferation depends on multiple oncogenes besides the oncogenic EGFR mutation, potentially resulting in a weaker oncogenic potential of EGFR and making EGFR-TKI monotherapy less effective as a front-line treatment." (PMID 36835536, 2023). "Abnormal overexpression and activation of epidermal growth factor receptor (EGFR) have been associated with various kinds of cancers." (PMID 36622089, 2023). "A high level of expression of EGFR has been linked to a reduced survival rate across several cancer types, and this expression acts as a strong prognostic indicator." (PMID 36676140, 2023). "Cancer cells have high densities of the EGFR, HER2, and HER3 causing phosphorylation of tyrosine amino acids on protein substrates and tyrosine amino acids near the C-terminal of the RTKs." (PMID 37508387, 2023). "In cancer cells, the two major characteristic alterations of EGFR are EGFR overexpression and mutations activating the tyrosine kinase domain." (PMID 38137520, 2023). "The results of our study indicated that PAI-1 is involved in osimertinib tolerance via EMT in EGFR-mutated cancer cells." (PMID 36831438, 2023). "This analysis evidenced that high levels of expression of both Sorcin and EGFR, considered as a signature, is associated with reduced overall survival in various cancer types, compared to low expression." (PMID 37442828, 2023). "The understanding of cancer genomic alterations has enabled the identification of potential diagnostic and therapeutic targets, one of which is EGFR." (PMID 37122754, 2023). "Loss of WTAP curbs cancer cell migration and invasion, potentially through the regulation of EGFR activity." (PMID 37964279, 2023). "In about one-third of the patients, this was due to emerging RAS mutations and cloning of cancer cells with BRAF mutations or EGFR ectodomain mutations as an escape mechanism from EGFR inhibition." (PMID 37927605, 2023). "FUT8 regulates the cancer-promoting capacity of cancer-associated fibroblasts by modifying EGFR core fucosylation." (PMID 37256139, 2023). "Sorcin and EGFR expression are significantly correlated and associated with reduced overall survival in cancer patients." (PMID 37442828, 2023). "Mutations in the EGFR gene are observed in many types of cancers; however, the recurrent mutated domains of EGFR in different cancer types vary." (PMID 38201434, 2023). "The EGFR mutation rate was calculated for each Cancer Alliance region as follows: EGFR mutation rate = [number of a:abnormal]/[(number of a:abnormal) + (number of b:normal)]." (PMID 37020004, 2023). "These EVs expressed the monoclonal antibody αCD3 UCHT1, which is specific for CD3 T cells, and single-chain variable fragments of αEGFR cetuximab, which is specific for cancer cell-associated EGFR." (PMID 37842166, 2023). "GSEA revealed that, compared with KC mice, KSC mice had an enrichment in stem cell networks (ESC pluripotency, Wnt, Notch, Hedgehog); EMT; a pancreatic ductal cell program; cancer-associated networks; and EGFR, ERBB2/HER2, and MET signaling pathways." (PMID 37643018, 2023).
cancer (continued). "Increased epidermal growth factor receptor (EGFR) activity is causally linked to many types of cancer." (PMID 37190033, 2023). "For example, EGFR (epidermal growth factor receptor, which plays an important role in the cancer process) activated mutations lead to constitutive tyrosine kinase activation and oncogenic transformation of lung epithelial cells." (PMID 36771198, 2023). "Summary of the neoantigens derived from cancer-associated EGFR mutations and associated clinical studies." (PMID 37766136, 2023). "An increase in MUC1—EGFR interaction leads to the activation of this factor, which is likely associated with tumorigenesis and cancer progression." (PMID 37345016, 2023). "We can easily anticipate the unfortunate involvement of this mutant variant of the receptor in human cancers given the significance of EGFR signaling in normal cell proliferation and differentiation." (PMID 37754880, 2023). "Increased EGFR levels also cause saturation of the endocytic and/or the ubiquitination machinery, which reinforces the sustained signaling in cancer cells." (PMID 37766136, 2023). "It is well known that EGFR is often mutated or overexpressed in various cancer types and is a target for anti-cancer therapies." (PMID 36831374, 2023). "Sorcin and EGFR showed association with survival in the majority of the considered cancer types even when evaluated individually." (PMID 37442828, 2023). "The patient had a particular type of bone metastases from primary cancers with genetic test results indicating EGFR amplification and mutation." (PMID 36701708, 2023). "In contrast, the amplification of the EGFR gene through ecDNA is frequently observed in cancer cells and is associated with invasiveness, heterogeneity, and radioresistance." (PMID 36859558, 2023). "The mutations in the EGFR protein activate a chain of events that constitutes subsequent growth and survival signaling in cancer cells." (PMID 36979929, 2023). "Studies indicate that GEF offers decent efficacy in Asian patients with EGFR mutation-positive cancer; hence, the mutation status of EGFR must be predetermined before treatment with GEF is commenced, particularly in a first-line clinical setting." (PMID 38090376, 2023). "Erlotinib, an EGFR tyrosine kinase inhibitor, is used for treating patients with cancer exhibiting EGFR overexpression or mutation." (PMID 37863665, 2023). "In BC, the establishment of protein signatures for circulating EVs (including EGFR, p-cadherin, and fibronectin) enabled differentiating cancer patients from healthy subjects and was further associated with cancer progression, and relapse." (PMID 38067168, 2023). "We infer that the enhanced EGFR degradation following Arl4A-depletion is unrelated to the EGFR degradation resistance machinery elicited by these cancer-associated EGFR mutations." (PMID 38030597, 2023). "In gallbladder carcinoma, loss of DSG2 was associated with cancer progression and resistance to EGFR-targeted therapy through activation of Src kinase." (PMID 38188287, 2023). "Taken together, these data demonstrated that PELI1 mediated EGFR stability through K63-linked ubiquitination to be involved in the aberrant EGFR signaling in cancers." (PMID 36841821, 2023). "Studies have reported that Dcn as a multivalent therapeutic agent against cancer by engaging multiple receptor tyrosine kinases like EGFR, Met and VEGFR2, and Dcn deficiency promoted epithelial-mesenchymal transition and colorectum cancer metastasis." (PMID 37464382, 2023). "This deacetylated Sia phenotype causes cancers to be more vulnerable to EGFR inhibitors (CIEAs and Sorafenib) and selectively provides an improved alternative approach through which they can be targeted and killed." (PMID 37687086, 2023). "Although established EGFR inhibitors have been effective in the treatment of cancer, they are associated with several sideeffects." (PMID 37808374, 2023).
cancer (continued). "Epidermal Growth Factor Receptor (EGFR) overexpression or its mutation mediates the sustaining proliferative signaling, which is an important hallmark of cancer." (PMID 37489364, 2023). "Due to mutation in the EGFR gene, an excess amount of EGFR protein is generated in some types of malignant cells, which causes a rapid cell division, and ultimately one or more malignant tumors result." (PMID 36768973, 2023). "Various types of cancers that are caused by overexpression of the EGFR gene, their possible molecular origins, and their natures have also been counted in this article." (PMID 36768973, 2023). "Erlotinib is a type of targeted cancer drug that targets mutated epidermal growth factor receptor (EGFR)." (PMID 37324942, 2023). "Epidermal growth factorreceptors (EGFRs), one of the tyrosinekinase receptors, are responsible for cell growth and proliferation.However, abnormal conditions in EGFR functions cause cancer." (PMID 37663500, 2023). "Increased EGFR activity is associated with numerous malignant tumors, including esophageal cancers, glioblastoma, anal cancers, epithelial cancers of the head and neck, breast cancer, and lung cancers, especially non-small cell lung cancer (NSCLC)." (PMID 37049777, 2023). "For instance, researchers have used covalently coupled epidermal growth factor receptor (EGFR)-targeting peptides or anti-EGFR nanobodies, causing them to accumulate in EGFR-positive cancer cells for targeted therapy." (PMID 37514088, 2023). "Numerous studies have shown that mutations activate the EGFR, and this discovery led to the approval of many cancer gene-targeted therapies, which altered cancer treatment worldwide." (PMID 37251081, 2023). "As the growth pattern of SIP topologically bears resemblance to cancer invasion, we investigated the effect of EGFR exon 20 mutations on cell migration and invasion abilities of cells exhibiting SIP-like growth pattern." (PMID 37891239, 2023). "Normal epithelial cells are transformed into mesenchymal phenotypes by OSCC-derived EVs, and cetuximab, an anti-EGFR therapeutic antibody, prevents this cancer-causing action." (PMID 37046817, 2023). "Approximately 40% of newly diagnosed GBMs exhibit an increase in the EGFR gene, and nearly half of these EGFR-amplified GBMs contain the constitutively active and cancer-causing EGFRvIII." (PMID 37900496, 2023). "For example, exosomes with the epidermal growth factor receptor EGFRvIII, released from glioma cells, can be taken up by EGFRvIII-deficient cancer cells, activating translational signaling pathways and enhancing growth ability." (PMID 36839784, 2023). "Mutations of EGF and EGFR were each found in only a single sample from our cohort and did not coincide with sites that are altered frequently in human cancers." (PMID 37079639, 2023). "It was suggested that, in addition to the degradation of the EGFR, these chemical compounds cause a strong detachment of cancer cells from the extracellular matrix, especially under conditions of cell starvation for EGF or glutamine." (PMID 37754201, 2023). "RNA-Seq analyses of GEM pancreata indicate that ST6GAL1 activity upregulates stem- and cancer-associated gene networks, promotes a pancreatic ductal cell program, and induces activation of EGFR." (PMID 37643018, 2023). "EGFR hasbeen linked to a variety of cancers, and its mutations, primarily missense mutations, inframe deletions, and others, have also beendocumented." (PMID 37808374, 2023). "Human epidermal growth factor receptor 2 (HER2) and epidermal growth factor receptor (EGFR) are mutated in multiple cancers including MIBC and are potential therapeutic targets." (PMID 36737799, 2023).